MTDH (metadherin)
Diseases named in the same sentence as MTDH in open-access papers (continued):
Sharing a sentence is not in itself a finding about the gene and the disease.
gallbladder adenocarcinoma (1 paper, 2014). A carcinoma that arises from glandular epithelial cells of the gall bladder. "The elevated expression of EphA7 and/or AEG-1/MTDH has also been found to closely correlate with the carcinogenesis, progression, clinical biological behavior and prognosis of gallbladder adenocarcinoma." (PMID 25009642, 2014).
invasive ductal carcinoma (1 paper, 2010). "We found high expressed MTDH in 72.97% of DCIS, but in 55.56% of invasive ductal carcinoma." (PMID 20565850, 2010).
male breast carcinoma (1 paper, 2012). A malignant neoplasm involving the male breast. "Also MED1, PRDM14, MTDH, and BIRC5 seem to be important in the development or progression of high grade male breast cancer." (PMID 22527098, 2012).
psoriasis (1 paper, 2023). An autoimmune condition characterized by red, well-delineated plaques with silvery scales that are usually on the extensor surfaces and scalp. "The diagnostic performance of miRNA-559 and MTDH in psoriasis was estimated by receiver operating characteristic (ROC) curve analysis." (PMID 36348199, 2023). "As well, our study targets to shed more light on the participation of miRNA-559 in the MTDH/PTEN/AKT signaling pathway regulation in psoriasis." (PMID 36348199, 2023). "Thus, miRNA-559 and MTDH might be proposed as promising diagnostic biomarkers of psoriasis." (PMID 36348199, 2023). "Further investigations are required to understand how MTDH can activate PI3K/AKT pathway in psoriasis and identify the precise role played by MTDH in psoriasis progression." (PMID 36348199, 2023). "Moreover, this study aimed at exploring participation of miRNA-559 in regulating MTDH/PTEN/AKT pathway in psoriasis." (PMID 36348199, 2023). "Together, the current findings provide the first suggestion of a new mechanism by which downregulation of miRNA-559 might induce proliferation in psoriasis through modulating PTEN/AKT/FOXO1 pathway by positive regulation of MTDH." (PMID 36348199, 2023). "This study intended to assess miRNA-559 and MTDH levels in skin and sera of psoriatic patients and to investigate their clinical significance in an attempt for developing novel distinct tools for early diagnosis of psoriasis." (PMID 36348199, 2023). "However, the expression profile and function of miRNA-559, and its direct target metadherin (MTDH), in psoriasis need to be further illuminated." (PMID 36348199, 2023). "Additionally, the inverse correlation between MTDH protein levels and miRNA-559 in psoriatic tissues may suggest that MTDH acts as an immediate target of miR-559 in psoriasis." (PMID 36348199, 2023). "Together, these findings demonstrate that downregulation of miRNA-559 in psoriasis may induce proliferation and inhibit apoptosis via PTEN/AKT pathway through positive regulation of MTDH expression." (PMID 36348199, 2023). "Taken together, the aim of the current study was to detect miRNA-559 expression and MTDH levels, not only in lesional and non-lesional tissues, but also in sera of psoriatic patients, and to investigate their biological role in psoriasis." (PMID 36348199, 2023). "Nevertheless, the function and biological roles of MTDH in psoriasis have not been clarified." (PMID 36348199, 2023).
renal carcinoma (1 paper, 2022). A carcinoma arising from the epithelium of the renal parenchyma or the renal pelvis. "In renal cancer, the study has been reported that MicroRNA−30a−5p inhibits the MTDH/PTEN/AKT pathway and leads to reducing the tumor cell proliferation of human renal cancer." (PMID 35127546, 2022).
renal fibrosis (1 paper, 2021). A final common manifestation of a wide variety of chronic kidney diseases characterized by glomerulosclerosis and tubulointerstitial fibrosis. "In the study of the unilateral ureteral occlusion (UUO) model, it was found that MTDH can promote renal fibrosis by regulating the EMT." (PMID 35153736, 2021). "It has been reported that MTDH may participate in the process of renal fibrosis by regulating the EMT process." (PMID 35153736, 2021).
Sepsis (1 paper, 2025). Sepsis is defined as life-threatening organ dysfunction caused by a dysregulated host response to infection. "According to current reports, miR‐21‐3p is also an important miRNA involved in immune regulation in inflammatory diseases; it regulates intestinal immunity by targeting downstream MTDH and SORBS2 to modulate sepsis‐induced cardiac inflammation." (PMID 40845083, 2025).
tuberculosis (1 paper, 2016). A chronic, recurrent infection caused by the bacterium Mycobacterium tuberculosis. "The MTDH was not influenced by the ethnicity of the TB patients or by M. tuberculosis culture status in extra-pulmonary TB patients." (PMID 27706152, 2016).
vascular tumors (1 paper, 2014). "AEG-1/MTDH overexpression converts non-tumorigenic human HCC cells into highly aggressive vascular tumors." (PMID 25009642, 2014).
viral infection (1 paper, 2022). "Moreover, the overexpression of MTDH greatly increased the expression of inflammatory cytokines and was associated with the severity of inflammatory response during viral infection." (PMID 36341362, 2022).
tumor (213 papers, 2009 to 2026). "Previous studies have implicated MTDH in tumor progression, metastasis, and poor clinical outcomes across various cancer types." (PMID 41286067, 2025). "An association between Metadherin expression and the tumor microenvironment was initially established by bioinformatic analysis in the present study." (PMID 38253625, 2024). "High expression of MTDH has been associated with tumor metastasis, decreased survival outcomes, and higher mortality in female reproductive cancers such as breast, ovarian, and cervical." (PMID 36902125, 2023). "What more, the differentially expressed genes between MTDH-high and MTDH-low tumor samples include EMT-associated genes, such as fibronectin (FN1), N-cadherin (CDH2), and SMAD." (PMID 34622157, 2021). "Generally, the elevated level of MTDH in cancer cells is considered a hallmark for the severity of tumor progression." (PMID 33802672, 2021). "Experiments confirmed that as a tumor suppressor in EN cells, miR-375 inhibited cell proliferation and invasion by repressing the expression of its direct target MTDH, an oncogene associated with tumorigenesis in EN." (PMID 34461870, 2021). "To further examine the association of MTDH with RKIP expression in tumor cells, we then performed a systemic analysis using public-access datasets where the MTDH gene was knocked down." (PMID 33802672, 2021). "In conclusion, we systematically investigated the expression of MTDH and its associations with cancer prognosis, immunotherapy response, tumor-infiltrating cells, and immune checkpoints in multiple independent cohorts." (PMID 34622157, 2021). "Metadherin (also known as astrocyte elevated gene 1 or LYRIC) is a tumour-associated antigen that promotes EMT, including downregulation of E-cadherin by activating multiple pathways, such as Wnt/β-catenin, MAPK, and PI3K/AKT signalling." (PMID 34572111, 2021). "The results showed that MTDH protein expression was strongly associated with the maximum diameter of tumor (MDT), histologic grade, and pathologic T stage." (PMID 31978894, 2020). "MTDH is highly expressed in a variety of malignant tumours and is associated with tumour progression through processes including initiation, proliferation, invasion, metastasis and chemoresistance." (PMID 32251289, 2020). "Increased MTDH levels were linked to the tumor chemoresistance making it an attractive novel therapeutic target." (PMID 31131259, 2019). "They rifely concluded that MTDH was associated with specific biological characteristics and molecular pathways related to tumor deterioration, but the exact mechanism was still unclear." (PMID 27917902, 2016). "The aim of this study was to determine the frequency and the spectrum of MTDH variants in tumor tissue, and their relationship to clinicopathological variables in CRC patients." (PMID 26983693, 2016). "During CRC development and aggressiveness, the AEG-1/MTDH mRNA and protein levels are upregulated and have been associated with tumor location and stage." (PMID 25009642, 2014). "NF-κB can promote inflammation-associated tumerigenesis and is related to the MTDH-associated tumor progression and metastasis in cervical cancers." (PMID 22195048, 2011). "MTDH is associated with tumor metastasis, drug resistance, and lipid metabolism." (PMID 41318030, 2025). "It appears that the main role of MTDH is associated with tumor chemoresistance and metastasis." (PMID 31131259, 2019). "Furthermore, MTDH is associated with the suppression of Twist1 expression, supporting the switch of tumor phenotype from mesenchymal to epithelial cells to accelerate metastatic colonization with epithelial plasticity." (PMID 29029495, 2017). "MTDH has been implicated in EMT process of several tumor cells." (PMID 28107197, 2017). "In conclusion, this is the first study analyzing MTDH mutations in tumor tissue." (PMID 26983693, 2016).
tumor (continued). "The aim of this study was to determine the frequency and the spectrum of MTDH variants in tumor tissue and their relationship to clinicopathological variables (patient gender, age at diagnosis, tumor location, tumor stage, grade of differentiation, recurrence and survival) of CRC patients." (PMID 26983693, 2016). "In order to enhance the statistical power and reach a recognized conclusion, we conducted a systematic review and meta-analysis to thoroughly investigate the association of MTDH expression with tumor metastasis and survival outcomes following PRISMA guidelines." (PMID 27917902, 2016). "These previous studies have confirmed that MTDH may activate signaling transduction pathways associated with tumor development, which may influence the biological features of the tumors." (PMID 25684730, 2015). "It remains elusive whether MTDH plays a causative role in LPS-induced tumor progression and metastasis." (PMID 22195048, 2011). "Therefore, MTDH could regulate the expression of tumor-associated genes, including RKIP by cooperating with other transcription factors." (PMID 33802672, 2021). "These expression studies suggest that MTDH may represent a potential tumor associated antigen." (PMID 31131259, 2019). "However, it is unknown whether mutations in the MTDH gene contribute to tumor progression and have prognostic potential for CRC." (PMID 26983693, 2016). "High level of MTDH was positively related to several clinicopathological parameters, including tumor stage, differentiation, and lymph node status." (PMID 42065055, 2026). "IAA activates the aryl hydrocarbon receptor (AHR), which subsequently blocks the NF-κB signaling pathway by competitively binding to MTDH in tumor cells." (PMID 41208900, 2025). "In highly metastatic (HM) ovarian cancer cells, the β-catenin signaling pathway is upregulated, leading to an increasing the expression of metadherin on the tumor cell surface." (PMID 40330466, 2025). "And, circHIPK3 is highly expressed in BC cell exosomes and promotes angiogenesis and tumor progression in endothelial cells by regulating the miR-124-3p/MTDH axis." (PMID 40274787, 2025). "The β-catenin-metadherin/CEACAM1-CCL3 axis plays a critical role in mediating metastatic heterogeneity by orchestrating interactions between metastatic tumor cells and TAMs." (PMID 40330466, 2025). "The MTDH gene, located on human chromosome 8, facilitates tumor cells adhesion to distant blood vessels, playing a critical role in cancer spread and metastasis." (PMID 40104500, 2025). "MTDH promotes tumor proliferation by inhibiting transcriptional factor FOXO1 and activating MEK/ERK and NFκB1 pathways, thereby driving tumor progression." (PMID 40149331, 2025). "MTDH S568 phosphorylation showed a significant increase in tumor samples compared to adjacent normal tissues (p-value < 0.0001), with a large spread across the analyzed tumors." (PMID 41286067, 2025). "Based on the HPA database, IHC was used to verify Metadherin protein expression in normal breast and tumor tissues." (PMID 38253625, 2024). "Oncoprotein Metadherin is widely involved in the malignant behavior of various tumors, and it has been shown to affect tumor cell proliferation, apoptosis, invasion, metastasis, and angiogenesis." (PMID 38253625, 2024). "Nevertheless, the role of USP7 and MTDH in the tumor microenvironment still needs further investigate in immune-competent mouse model to identify their effects in immunoregulation." (PMID 38625581, 2024). "In progressive tumors, exosomal circHIPK3 released from tubular BC cancer cells modulates angiogenesis within the tumor by sponging and inhibiting the action of miR-124-3p on the MTDH gene in endothelial cells on the tumor periphery." (PMID 39795985, 2024). "Collectively, USP7 promoted CC cell proliferation, migration, invasion, angiogenesis, and macrophage M2 polarization in vitro, as well as tumor growth in vivo by regulating MTDH." (PMID 38625581, 2024).
tumor (continued). "Since we showed that MTDH depletion plays a key role in proliferation, tumor spheroid formation, and IBC cell motility, we then investigated how key signaling pathways related to these functions are affected." (PMID 36902125, 2023). "Subsequently, the presence of MTDH was validated in IBC tissues and within tumor emboli, a hallmark of IBC metastasis." (PMID 36902125, 2023). "MTDH has been correlated with BC progression and poor overall survival in patients, but its role in regulating tumor cell proliferation remains controversial." (PMID 36902125, 2023). "They exerted their anti-tumor actions at least in part via Metadherin (Mtdh), which is recognized as a therapeutic target of multiple cancers including breast cancer." (PMID 36923539, 2023). "We also demonstrated the effects of MTDH depletion on early tumor development and metastasis in xenograft models." (PMID 36902125, 2023). "Both gene lists contained genes associated with tumor progression and metastasis, such as CDK6, SNED1, and MTDH." (PMID 37234983, 2023). "Our results show that MTDH depletion only reduced tumor volume in the early stages of the study, however the reduction was not sustained." (PMID 36902125, 2023). "For example, MTDH has been reported to affect the function of PI3K/AKT pathway genes directly or indirectly and is associated with tumor cell survival, metastasis, and drug resistance." (PMID 36071474, 2022). "Western blot and immunohistochemical analysis of tumor samples indicated successful knockdown of metadherin and reduction of metadherin by β‐catenin knockdown." (PMID 35403834, 2022). "Metadherin knockdown significantly decreases omental metastasis and the number of tumor nodules in these mice (2.3‐fold)." (PMID 35403834, 2022). "miRNA-375 exerts its tumor-suppressive function by reducing the expression of metadherin (MTDH) and phosphorylation and cell viability depending on Akt-Ser473, regulating cell proliferation and viability." (PMID 35966515, 2022). "Using single‐cell live imaging, we also provide evidence for a cell surface metadherin/CEACAM1‐CCL3 positive feedback loop which gives rise to the formation of polyploid tumor cells." (PMID 35403834, 2022). "Our data indicate that MTDH was highly expressed in tumor tissues compared to normal tissues along with a lower frequency of genetic alterations of the MTDH gene." (PMID 33802672, 2021). "We found that the expression of MTDH was significantly higher in tumor tissues compared to control tissues." (PMID 33802672, 2021). "To systematically investigate the mRNA expression of MTDH in pan-cancer levels, we performed the pairwise comparisons of MTDH mRNA in tumor samples and paired-adjacent normal tissues in the available 22 kinds of cancers from the TCGA dataset." (PMID 34622157, 2021). "In another study, the expression of miR-375 was significantly downregulated in APAs, whereas the respective in vitro experiments implied a role in tumor suppression acting through the metadherin (MTDH)/Akt pathway." (PMID 34771744, 2021). "The significant correlations of MTDH expression with estimated scores of tumor-infiltrating immune cells were visualized in a heatmap." (PMID 34622157, 2021). "MTDH is highly expressed in many types of cancers, and involved in tumorigenesis and tumor progression in multiple aspects." (PMID 35046810, 2021). "Metadherin (MTDH) functions as an oncogene that facilitates tumor cell invasion and migration, resulting in poor prognosis." (PMID 35046810, 2021). "The results showed that silencing MTDH inhibited tumor size, promoted Gem on inhibiting tumor size, and reduced tumor weight of the model mice." (PMID 34552061, 2021).